TFGP1 (TFG pseudogene 1)
Gene: Processed pseudogene on chromosome 6 (38,587,323 to 38,588,529, forward strand). Ensembl gene ENSG00000217227.
Diseases named in the same sentence as TFGP1 in open-access papers:
TFGP1 is named in the same sentence as 1 disease in open-access papers, as found by Europe PMC text mining. Sharing a sentence is not in itself a finding about the gene and the disease. The quoted sentences say what the papers report.
tumour (1 paper, 2024). "Apart from SKP2, ITGB4, CDKN3, TFGP1, SLCO1B3, CDX2 and KIF18A, the remaining model genes showed significant correlations with stem cell score, immune score and tumour microenvironment." (PMID 39656479, 2024).